ADAM17 (ADAM metallopeptidase domain 17)
Diseases named in the same sentence as ADAM17 in open-access papers (continued):
Sharing a sentence is not in itself a finding about the gene and the disease.
tumor (continued). "ADAM10 and ADAM17 cleave PD-L1 from the surface of tumour and respiratory tract cells." (PMID 37816808, 2023). "As NOX1 is expressed by tumor cells and host cells, in particular endothelial cells, and regulates ADAM17 activation and sMCAM release, we next assessed whether ADAM17 or sMCAM tumor-promoting functions would act downstream of NOX1." (PMID 38137406, 2023). "Silencing ADAM17 expression in GBM tumor cells was correlated with low level of sLRIG3 protein in cellular supernatant, which indicating that ADAM17 may modulate the release of sLRIG3." (PMID 36639372, 2023). "ADAM17 expression in the tumours was confirmed by immunohistochemistry (IHC)." (PMID 38069391, 2023). "In addition, the immunomodulatory effect of ADAM17 on tumour development has attracted attention in recent years." (PMID 38069391, 2023). "These experiments indicate that ADAM17 inhibition directly affects MC38 and DLD1 tumor cells, but not LoVo cells lacking mature ADAM17 due to furin deficiency." (PMID 38137406, 2023). "Notch pathway activation is controlled by the cleavage of Notch proteins/receptors mediated by A disintegrin and metalloproteinase 17 (ADAM17); therefore, ADAM17 is a reliable intervention target for anti-tumour therapy to overcome the drug resistance of cancer cells." (PMID 37456760, 2023). "In tumor mice with an overall therapy response, expression of genes encoding the proteases ADAM8, ADAM10, and ADAM17 was increased and might contribute to the immunosuppressive phenotype of GB and immune cells." (PMID 38139457, 2023). "Furthermore, bioinformatics revealed that elevated ADAM17 expression was negatively correlated with miR-145 levels, which was in turn correlated with tumor malignancy and poor survival." (PMID 37175410, 2023). "Interestingly, it has been previously shown that ADAM10 and ADAM17 expression and enzymatic activity are induced by irradiation and that the depletion of these proteases radiosensitize tumor cells." (PMID 37495855, 2023). "Several ADAM17 substrates are relevant to oncogenesis and tumor growth." (PMID 37623781, 2023). "Tumor-bearing mice were then treated with the ADAM17 inhibitor TMI-5." (PMID 38137406, 2023). "Our demonstration that mutant FGFR2 enhances the sensitivity to FGF7‐induced ADAM17 activity provides an explanation of how these tumours might adapt in an environment with reduced growth factors." (PMID 37165578, 2023). "However, we here demonstrate that ADAM17 also regulates tumor cell migration as part of a paracrine process." (PMID 36998455, 2023). "Interestingly, we demonstrated that targeting ADAM17 encompasses the NOX1-sMCAM pathway but offers additional anti-tumor effects that regulate TAM recruitment." (PMID 38137406, 2023). "We explored the oncogenic effects of ADAM17 in a subcutaneously implanted tumour model." (PMID 38069391, 2023). "Because ADAM17 is the subsequent step following FGFR2 activation in migration and proliferation of EM cells, targeting ADAM17 function in FGFR2‐mutant EC cells may have a beneficial effect in tumour suppression." (PMID 37165578, 2023). "In recent studies, miR-145 has been proven to inhibit the proliferation, invasion, and metastasis of tumor cells; increase the sensitivity of tumor cells to chemotherapy; and regulate the occurrence and development of tumors by targeting ADAM17 in several malignant tumors." (PMID 37175410, 2023). "Furthermore, the inhibition and genetic deletion of ADAM17 resulted in a significant reduction of xenografted tumour size and weight in all experimental mice." (PMID 37165578, 2023). "Thus, ADAM knockdown effects on RB tumor formation in vivo confirmed the in vitro effects on cell growth, displaying high effects after ADAM17 and ADAM10/17 and only moderate after ADAM10 knockdown." (PMID 36293469, 2022).
tumor (continued). "Our previous study indicated that hypomethylation of ADAM17 in PAAD tumor tissues was positively correlated with high ADAM17 expression, indicating that hypomethylation of the ADAM17 promoter may be responsible for its increased expression in PAAD tissues." (PMID 36558177, 2022). "However, its immunomodulatory functions and mechanisms in cancer diseases are not well studied, and therefore more studies are needed to further determine the role of ADAM17 in tumor development." (PMID 36466812, 2022). "In conclusion, hypomethylation of ADAM17 was positively correlated with high ADAM17 expression in PAAD tumor tissues, suggesting that hypomethylation of the ADAM17 promoter may be responsible for the increased ADAM17 expression in PAAD tissues." (PMID 36558177, 2022). "Currently approved clinical trials using ADAM17 inhibitors for tumor treatment." (PMID 36466812, 2022). "Importantly, we highlighted the immunomodulatory roles of ADAM17 in tumor development, as well as small molecule inhibitors and monoclonal antibodies targeting ADAM17." (PMID 36466812, 2022). "Photo-documentation of CAM tumors developing from inoculated RB cells and quantification of tumor weight and size revealed that ADAM17 single and ADAM10/17 double depleted RB cells develop significantly smaller tumors than control cells, with lower weight and size." (PMID 36293469, 2022). "ADAM17 is found to be overexpressed in a large set of tumors, including breast, colon and liver cancer, and has been linked to autocrine activation of epidermal growth factor receptor (EGFR) on tumor cells." (PMID 36078095, 2022). "Expression of ADAM10 and ADAM17 was elevated in all tumor sets analyzed." (PMID 36078095, 2022). "Furthermore, ADAM17 is able to promote tumor growth via induction of inflammatory processes, such as TNF α signaling and interleukin 6 (IL-6) trans-signaling." (PMID 36078095, 2022). "However, further analyses regarding the involvement of ADAM10 and ADAM17 in blood vessel sprouting in RB tumor development are needed to address the question properly." (PMID 36293469, 2022). "On the one hand, although the regulatory effect of ADAM17 on macrophages, NK cells, and endothelial cells has been confirmed in tumor, more key proteins or genes related to ADAM17 need to be identified, and the immune response involved in TME needs to be further explored." (PMID 36466812, 2022). "Furthermore, the authors used cellular co-culture and zebrafish embryo propagation models to demonstrate that tumor cells, in an ADAM17-dependent manner, drive macrophage polarization into a tumor-promoting phenotype and accelerate tumor cell invasion." (PMID 36466812, 2022). "Indeed, most of the papers reporting IHC analyses of ADAM17 expression in tumor tissues employed an evaluation method based on a semiquantitative weighted histoscore, which combines staining intensity and percent of positive cells." (PMID 36140519, 2022). "Interestingly, ADAM17 expression significantly correlated with immunomodulators and immune cell infiltration in normal and tumor tissues." (PMID 35720350, 2022). "However, in another study related to oncogenic KRAS, KRAS mutations triggered enhanced ADAM17-mediated NPG1 shedding of the SLC3A2-NPG1 fusion protein, which in turn promoted tumor cell growth." (PMID 36466812, 2022). "The concentration of ADAM10 was higher in the surgical margin than in the tumor (249.34 vs. 228.82 pg/μg protein), and the concentration of ADAM17 was higher in the tumor than in the margin (0.23 vs. 0.18 ng/μg protein), but results were not statistically significant." (PMID 36286024, 2022). "Therefore, studying the key role and immunomodulatory mechanisms of ADAM17 in tumor development will provide new strategies for the prevention, diagnosis and treatment of cancer diseases." (PMID 36466812, 2022).
tumor (continued). "In addition to affecting membrane protein shedding, ADAM17 also induces local tumor metastasis and invasion through degradation of the cellular basement membrane and extracellular matrix." (PMID 36558177, 2022). "ADAM17 protein is located in the membrane and cytoplasm in distinct tumor tissues." (PMID 35720350, 2022). "We selected the cases of ADAM17 and MMP14 targets to illustrate the potential of our methodology, as they have been implicated in tumour evasion through metalloproteinase function and catalysis of cleavage of endogenous MHC class I-related chain molecule (MIC) A and B." (PMID 35379165, 2022). "This study compared ADAM17 expression between normal and tumor tissues based on GEPIA." (PMID 35720350, 2022). "Vessel formation toward the tumor spheroids almost doubled over 72 hours (d11 to d14) in IgG1-treated tumor spheroids was halted in response to irradiation and only slightly increased on ADAM17 inhibition within the treatment period." (PMID 36860547, 2021). "A potential impact of these studies is that blocking ADAM17 may provide a therapeutic approach to increase NK cell proliferation by IL-15 and their anti-tumor function in patients." (PMID 34367174, 2021). "The large repertoire of substrates processed by ADAM17 include molecules that are crucial for tumour immunosurveillance, and the study of the shedding mechanisms coordinated by this protease has led to the proposal of novel events of resistance to noted cancer therapies." (PMID 34362154, 2021). "In the case of advanced tumor stage, this indicates that tumor-derived ADAM17 could primarily be released into malignant ascites and then secondarily transferred from ascites into the patient’s blood." (PMID 34771725, 2021). "From these parental Colo-320 cells we previously generated two stable cell lines, Colo-320/CD9 and Colo-320/ADAM17-KO, which allowed us to study here the specific involvement of CD9 and ADAM17 in the interactions and uptake of tumor exosomes by recipient cells." (PMID 34576100, 2021). "In order to investigate whether ADAM17 may predict primary debulking efficiency, the proportion of patients without macroscopic tumor remnants (48 cases) was compared to those with residual tumor burden (35 cases), with regard to ADAM17 serum levels." (PMID 34771725, 2021). "It is well-known that ADAM17 promotes tumor progression, metastasis, and cell invasion." (PMID 33922533, 2021). "Based on these facts, miR145 could induce tumor cell apoptosis in TT through mediating the expression of certain apoptotic genes including ADAM17 gene expression." (PMID 34959623, 2021). "ADAM17, which is at the focus of this study, has been demonstrated as a key sheddase controlling ectodomain cleavage of various substrates involved in metastasis, tumor progression, and therapy resistance." (PMID 34208863, 2021). "Likewise, irradiation-induced secretion of VEGF was also suppressed in tumor cells expressing the ADAM17-directed shRNA construct in comparison to tumor cells transduced with the control shRNA construct." (PMID 36860547, 2021). "Other tumor suppressor miR-152 showed an inversely correlation with the expression of ADAM17." (PMID 34182543, 2021). "Immunosuppression of T-cell response by MDSC may be accomplished through cleavage of L-selectin on CD4+ and CD8+ T-cells by ADAM metallopeptidase domain 17 (ADAM17) and disintegrin thus impairing T-cell trafficking to tumor sites." (PMID 33679798, 2021). "However, as the regulation and pathophysiology of ADAM17 in cancer and especially in tumor-educated platelets is complex, further elucidation is warranted." (PMID 34208863, 2021). "ADAM17 works upstream of all these pathways and thus might be a valuable alternative target to reduce tumor growth and overcome drug resistance." (PMID 33922533, 2021). "All these suggested that inhibitors of ADAM17 and may be correlated to the tumor targeted therapy selection." (PMID 34182543, 2021).
tumor (continued). "The aim of this study was to analyze whether ADAM17 inhibition also sensitizes cells to cisplatin in a more complex 3D tumor spheroid model." (PMID 33922533, 2021). "Thus, only spheroids derived from wild-type tumor cells (A549, H358) were treated in the later experiments with the control antibody IgG1 and the ADAM17-inhibitory antibody MEDI3622 (25 μmol/L, day 11), respectively, and irradiated (5 Gy) 24 hours thereafter." (PMID 36860547, 2021). "Indeed, some ADAMs are expressed in malignant tumors and participate in cancer pathology with ADAM10 and ADAM17 playing a prominent role for this mechanism of tumor immune-evasion by controlling MICA and MICB." (PMID 33789714, 2021). "Since PROCR knockdown could significantly ameliorate tumor growth in transplantation, the therapeutic potential of ADAM17 in TNBC is worth investigating." (PMID 34281556, 2021). "Blocking ADAM17 activity in tumor cells can also enhance NK cell cytotoxicity." (PMID 34367174, 2021). "The impact of these findings is that blocking ADAM17 function in combination with IL-15 stimulation may provide a new therapeutic approach to increase NK cell proliferation and their anti-tumor function in patients." (PMID 34367174, 2021). "ADAM17 (A disintegrin and metalloproteinase 17) is a membrane-bound protease that cleaves various cell surface proteins, including cytokines and cytokine receptors, and is highly expressed on tumor cells." (PMID 33535627, 2021). "Therefore, it is likely that not only the tumor itself but also the surrounding microenvironment expresses ADAM17 and releases it into the bloodstream as a result of inflammation and response to the invasive growth of the carcinoma." (PMID 34771725, 2021). "This would explain the high ADAM17 levels in the blood, despite a low tumor burden." (PMID 34771725, 2021). "Notably, ADAM10 and ADAM17 (TACE) play roles in gastroenterological tumors, contributing to different processes, such as a reduction in DNA damage repair, tumor growth, vascularization, and in the control of inflammatory responses in the intestine." (PMID 34204509, 2021). "For example, the proteases ADAM10 and ADAM17, expressed at the surfaces of different tumor cell types, may cleave the extracellular domains of the NKG2D ligands, MICA and MICB, and that of the NKp30 ligand, B7-H6." (PMID 32272610, 2020). "Overall, MALAT1 deletion could strengthen the sensitivity response to Ox via miR-324-3p/ADAM17 axis in xenograft tumor model." (PMID 33005106, 2020). "Recent studies have determined that ADAM17 dysfunction may play an important role in tumor invasion." (PMID 33100908, 2020). "Moreover, the formation of neoplasias stimulated ADAM17 on macrophages, leading to EGFR ligand cleavage and subsequent EGFR stimulation." (PMID 32864098, 2020). "Furthermore, there is evidence that ADAM17 on intestinal tumour cells promotes tumour angiogenesis through enhanced vascular endothelial growth factor (VEGF)-A secretion." (PMID 32698506, 2020). "The specific role of ADAM17 in CRC, however, appears to be multifaceted as all three major ADAM17-regulated pathways (TNFα-, EGF-R- and IL-6-signaling) on different cell types are implicated in tumor progression." (PMID 33143292, 2020). "In addition, there is evidence that the release of EGFR ligands from cancer associated macrophages depends on ADAM17 and it was demonstrated that myeloid EGFR activation is a prerequisite for the release of tumour-promoting IL-6." (PMID 32698506, 2020). "ADAM17 inhibitor can effectively inhibit the growth and invasiveness of tumor cells, which may be used in cancer treatment in the future." (PMID 32610677, 2020). "Overexpression of ADAM17 may improve tumor processing by cleaving the prodomain of MMP21 and activating it." (PMID 33100908, 2020). "Nevertheless, in the tumor, mCX3CL1 may be cleaved by proteinases such as ADAM10 or TACE/ADAM17, which releases the chemokine domain and thereby reduces the level of mCX3CL1 on a tumor cell." (PMID 32466280, 2020).
tumor (continued). "Shedding of NKG2DL by ADAM10 (and/or ADAM17) in turn impairs tumor-cell lysis by NK cells." (PMID 32117229, 2020). "CD16 cleavage might be mediated by either over-activation of the NK cells by the tumor itself or the inflammatory tumor microenvironment, as ADAM17 can be triggered by both activating and cytokine receptors." (PMID 32961861, 2020). "Moreover, we found that decreased MALAT1 and ADAM17 expression and increased miR-324-3p expression were found in tumor tissues isolated from sh-MALAT1 mice treated with Ox." (PMID 33005106, 2020). "Moreover, in a xenograft model with ADAM17-deleted A549 cells, tumor formation was abrogated as compared to unedited A549 cells." (PMID 31694340, 2019). "Moreover, inhibition of ADAM17 using genetic and prodomain inhibitor approaches significantly impaired tumour growth in LAC models and xenografts." (PMID 31438559, 2019). "In proof‐of‐concept preclinical studies involving genetically engineered and xenograft (human cell line and patient‐derived) KRAS mutant LAC models, the genetic and therapeutic targeting of ADAM17, the latter with a new class of specific ADAM17 prodomain inhibitor, markedly suppressed tumor growth." (PMID 30833304, 2019). "We showed recently that this mechanism does not induce proliferation in normal human fetal liver cells positive for CD326, in contrast to tumor cells; moreover, gene knockdown or treatment with an inhibitor of ADAM17 rather increased the number of CD326-positive normal fetal liver cells." (PMID 31011334, 2019). "However, expression levels of ADAM17 mRNA and pro (120 kDa)‐ and mature (90 kDa) protein forms were comparable in the lungs of KrasG12D mice and tumor‐free KrasWT controls." (PMID 30833304, 2019). "Indeed, both the levels and activity of ADAM17 were found augmented in inflamed and/or tumour tissues." (PMID 30709842, 2019). "Among ADAM17 substrates, IL‐6R, TNFα, Notch1, and EGFR family ligands (e.g., TGFα, amphiregulin, epiregulin, and neuregulin‐1) promote the proliferation, survival, migration, and/or invasion of tumor cells (Zunke & Rose‐John, 2017), thus suggesting a prominent role for ADAM17 in cancer." (PMID 30833304, 2019). "Of note, ATII and club cells have been identified as the cells of origin of mutant Kras‐driven LAC, thus suggesting that ADAM17 may contribute to tumor initiation in the lung." (PMID 30833304, 2019). "Next, we examined whether the FoxM1-ADAM-17 axis played a key role on tumor growth by downregulating the expression of FoxM1 and ADAM-17." (PMID 29776401, 2018). "General tumor-suppressing effects of ADAM17 blockage have been demonstrated in previous studies." (PMID 29662625, 2018). "Additionally, both ADAM10 and ADAM17 cleave various other membrane proteins and promote tumor in the cell." (PMID 29560732, 2018). "Moreover, overexpression of ADAM17 decreased the effect of chemotherapeutic treatment on tumor growth and apoptosis." (PMID 29662625, 2018). "Besides TNFα and substrates involved in tumor immunosurveillance, there are over 20 substrates for ADAM17 that are regulators of inflammation." (PMID 29230082, 2017). "Therefore, targeting ADAM17 to reduce soluble ligand levels would increase cellular immune responses to tumor cells." (PMID 29230082, 2017). "However, ADAM17 also has substrates that act as tumor suppressors such as Klotho and p75 neurotrophin factor." (PMID 29230082, 2017). "In the present study, we explored whether ADAM17 in CD133-expressing liver CSCs plays a key role in radiation-induced tumor cell invasiveness or the metastatic potential of HCC." (PMID 26993601, 2016). "Additionally, ADAM17 plays important roles in tumor progression, hypoxia-induced tumor cell invasiveness and hypoxia-induced cisplatin resistance." (PMID 26993601, 2016).